CIP2A (cellular inhibitor of PP2A)
Diseases named in the same sentence as CIP2A in open-access papers (continued):
Sharing a sentence is not in itself a finding about the gene and the disease.
gastric cancer (22 papers, 2010 to 2025). A primary or metastatic malignant neoplasm involving the stomach. "The migration pattern of this 90 kDa protein is similar to the previously identified tumor-associated antigen, CIP2A, in gastric cancer." (PMID 26560124, 2015). "CIP2A is involved in sustaining proliferation through preventing cell growth arrest, senescence or differentiation, and its expression level is inversely associated with clinical prognosis of gastric cancer." (PMID 37470692, 2023). "Polyphyllin I restricted the proliferation and invasion of the cisplatin-resistant gastric cancer cell line SGC7901/DDP via the modulation of the CIP2A/PP2A/Akt pathway." (PMID 37568716, 2023). "Consistent to our previous study, CIP2A exerts its anti-proliferative and pro-apoptotic effects of celastrol on gastric cancer cells." (PMID 37470692, 2023). "In conclusion, celastrol is expected to be applied to the clinical treatment of gastric cancer by targeting an oncoprotein CIP2A." (PMID 37470692, 2023). "H. pylori wt infection activated the Cancerous Inhibitor of PP2A (CIP2A) upstream regulator that is overexpressed in gastric cancer." (PMID 37193047, 2022). "There was a report that CIP2A protein can promote proliferation of gastric cancer cell and the inhibition of CIP2A makes the tumor cells undergo senescence." (PMID 26894380, 2016). "An increased expression of CIP2A protein was found in cholangiocarcinoma, gastric cancer, breast cancer, prostate cancer, lung cancer and in head and neck squamous cell carcinomas." (PMID 26894380, 2016). "CIP2A stabilizes c-Myc by inhibiting PP2A, but c-Myc stimulates CIP2A mRNA and protein expression in gastric cancer." (PMID 25650660, 2015). "In gastric cancer, helicobacter pylori infections up-regulate CIP2A expression through a Src/Erk dependent pathway." (PMID 24098375, 2013). "CIP2A has been reported to be overexpressed in several human cancers, including head and neck squamous cell carcinoma, colon cancer, and gastric cancer." (PMID 23342256, 2012). "Higher CIP2A expression has been shown as a prognostic factor predicting survival in gastric cancer, non-small cell lung cancer, renal cell carcinoma, serous ovarian cancer and early stage tongue cancer." (PMID 22537901, 2012). "In gastric cancer, Helicobacter pylori infection up-regulates CIP2A expression through the Src and ERK pathways." (PMID 22075943, 2011). "CIP2A is over-expressed in human neck and head carcinomas, colon, breast, and gastric cancer, and is inversely correlated with disease outcome in gastric cancer." (PMID 21655278, 2011). "In gastric cancer cell lines, induction of CIP2A expression following Helicobacter pylori infection was dependent on Src and Ras/mitogen-activated protein kinase kinase/extracellular signal-regulated kinase pathways." (PMID 20964854, 2010). "The CIP2A protein is expressed in human gastric cancer, and it promotes proliferation of gastric cancer cells." (PMID 20964854, 2010). "SET and CIP2A are overexpressed in gastric cancer and inhibit PP2A activity." (PMID 41220952, 2025). "Furthermore, CIP2A, which is expressed in multiple cancer types, including gastric cancer, has been reported to regulate key proliferation pathways such as AKT." (PMID 41155583, 2025). "Our study was designed to explore the anti-cancer effect of celastrol, a small natural compound, and whether it has an anti-proliferative effect through inducing CIP2A degradation against gastric cancer cells." (PMID 37470692, 2023). "Furthermore, available clinical trial data indicated CIP2A was a useful predictive marker of poorer prognosis of gastric cancer, NSCLC, ovarian cancer and chronic myeloid leukemia." (PMID 37470692, 2023). "Cancerous inhibitor of PP2A (CIP2A)—also known as KIAA1524 or p90 tumor-associated antigen—is a human oncoprotein that is overexpressed in human neck and head carcinomas as well as breast, colon, and gastric cancers." (PMID 27144172, 2016).
gastric cancer (continued). "However, another study showed that only Ets-1 is required to regulate CIP2A expression in prostate and gastric carcinoma." (PMID 25537503, 2015). "MYC-dependent regulation and prognostic role of CIP2A is reported in gastric cancer." (PMID 25015035, 2014). "In comparison with lung and gastric cancers, in tongue cancer CIP2A expression is more intense." (PMID 21610708, 2011). "Furthermore, CIP2A has prognostic significance in certain subgroups of gastric cancer." (PMID 20964854, 2010). "Protein phosphatase 2A (PP2A), a well-established tumor suppressor, is functionally impaired in gastric cancer due to the overexpression of endogenous inhibitors such as SET and CIP2A." (PMID 41220952, 2025). "We hypothesized that CIP2A is an important target of celastrol and celastrol is capable of inducing apoptosis and growth inhibition through inducing CIP2A degradation mediated proteasome complex and activating its downstream signaling pathway in gastric cancer cell." (PMID 37470692, 2023). "CIP2A plays an essential role in tumor metastasis and EMT and its upregulation is often observed in gastric cancer." (PMID 37568716, 2023). "In addition, a previous report showed comparable CIP2A expression in S-phase synchronized and unsynchromized gastric cancer cells, so cell cycle activity may not be associated with c-Myc-mediated regulation of CIP2A expression in gastric cancer cells." (PMID 25650660, 2015). "In the gastric cancer cells line SGC7901/DDP, PPI could induces apoptosis by regulating CIP2A/PP2A/AKT pathway gene expression." (PMID 38324023, 2024). "Increasing evidence demonstrated CIP2A in ovarian cancer, gastric cancer, colon cancer and non-small-cell lung cancer was overexpressed." (PMID 37470692, 2023). "Our work provides further understanding of CIP2A-GSK3β-MCL-1 regulatory axis in tumorigenesis and may present celastrol as a novel therapy for gastric cancer." (PMID 37470692, 2023). "This is in agreement with results of previous studies; for instance, in gastric cancer, CIP2A was detected in tumor tissues but not in normal gastric mucosa, and depleting CIP2A expression suppressed the growth of tumor cell lines." (PMID 27144172, 2016).
colon carcinoma (21 papers, 2011 to 2025). "CIP2A overexpression is also associated with colon cancer cell proliferation, tumorigenesis in vitro, and resistance to cetuximab, 5-fluorouracil, oxaliplatin and SN38 (an active metabolite of irinotecan)." (PMID 25896895, 2015). "For instance, in colon cancer, Cancerous inhibitor of protein phosphatase 2A (CIP2A) can be upregulated by ATF6 and contributes to poor prognosis." (PMID 41050076, 2025). "Temsirolimus enhances the efficacy of cetuximab in the treatment of colon cancer by targeting CIP2A expression." (PMID 35872794, 2022). "For instance, ER stress-related ATF6 upregulated cancerous inhibitor of protein phosphatase 2A (CIP2A), which contributes to colon cancer cell survival and indicates a trend toward poor prognosis." (PMID 33267910, 2020). "Mechanistically, we found that ATF6 directly bound to the CIP2A promoter and induced CIP2A gene expression, which contributed to colon cancer cell survival." (PMID 30063110, 2018). "In the present study, we demonstrated that the ATF6‐CIP2A pathway is essential to colon cancer cell survival, and CIP2A serves as a biomarker in clinical prognosis." (PMID 30063110, 2018). "In conclusion, our present study provides evidence of linkage between ER stress and CIP2A, while conditional ER stress‐related ATF6 upregulates CIP2A and contributes to the prognosis of colon cancer." (PMID 30063110, 2018). "We further investigated the prognostic value of ATF6 and CIP2A expression, independently, in patients with colon cancer and CRC." (PMID 30063110, 2018). "Taken together, our results show that ER stress‐related ATF6 upregulates CIP2A and contributes to the prognosis of colon cancer." (PMID 30063110, 2018). "Most importantly, immunohistochemical analysis of a tissue microarray from a colon cancer patient cohort showed that higher expression levels of ATF6 and CIP2A were associated with a trend toward poor prognosis." (PMID 30063110, 2018). "To determine the clinical significance of ATF6 and CIP2A expression in colon cancer, we analyzed the relationship between ATF6 protein expression and various clinicopathological parameters in a total of 165 patients with colon cancer." (PMID 30063110, 2018). "The results indicated that CIP2A sustains the survival of colon cancer cells through ATF6 under ER stress conditions." (PMID 30063110, 2018). "Due to the importance of ATF6 signaling in the survival of cancer cells, we next evaluated the effect of CIP2A knockdown in colon cancer cells." (PMID 30063110, 2018). "We found that the expression of ATF6 was positively correlated with the expression of CIP2A not only in patients with colon cancer but also in both the colon cancer cell line and the immortalized normal cell line under ER stress." (PMID 30063110, 2018). "The results showed that knockdown of CIP2A reduced cell viability in the presence of tunicamycin in HCT15 and SW480 cells, indicating that basal expression of CIP2A was necessary for colon cancer survival in ER stress." (PMID 30063110, 2018). "In this context, the HDACi (S)-2 represented the tool capable of unleashing PP2A activity by inducing HDAC1-mediated downregulation of CIP2A transcription in human colon cancers." (PMID 27029072, 2016). "CIP2A was found to be a prognostic marker in colon cancer patients with weak expression of pERK or pAKT and potential biomarkers for CIP2A inhibitors include pERK and pAKT." (PMID 25015035, 2014). "CIP2A mRNA was amplified / overexpressed in colon tumor samples and CIP2A expression levels correlated significantly with tumor stage." (PMID 25015035, 2014). "Our data support the notion that deregulated expression of CIP2A is a critical oncogenic event in colon carcinoma." (PMID 24098375, 2013). "We also found that shRNA-mediated depletion of CIP2A in HCT116 colon carcinoma cells markedly reduced their growth potential." (PMID 24098375, 2013).
colon carcinoma (continued). "CIP2A mRNA was overexpressed in colon cancer samples and CIP2A expression levels correlated significantly with tumour stage." (PMID 24098375, 2013). "Further, we investigated CIP2A-dependent effects on levels of c-Myc, Akt and on cell proliferation in three colon cancer cell lines by silencing CIP2A using small interfering (si) and short hairpin (sh) RNAs." (PMID 24098375, 2013). "The notion that CIP2A is overexpressed in colon cancer, thereby enhancing Myc protein levels and influencing tumour related survival, is consistent with previous results in other solid tumours." (PMID 24098375, 2013). "First, we analysed expression of CIP2A in a cohort of 104 colon cancer patients with documented follow-up and confirmed its overexpression." (PMID 24098375, 2013). "Cancerous inhibitor of protein phosphatase 2A (CIP2A) is a human oncoprotein overexpressed in head and neck squamous cell carcinoma and in colon cancer." (PMID 21897396, 2011). "Bortezomib was found to cause decreased CIP2A expression in colon cancer, while its use in triple negative breast cancer resulted in reduced CIP2A mRNA expression and no variation in CIP2A degradation." (PMID 38184584, 2024). "Additionally, the analysis of 21 colon cancer (CRC) patients showed a decrease in PP2A activity, which was likely caused by the observed overexpression of both SET and CIP2A in CRC as well as the downregulation of the regulatory subunits, PPP2R2A and PPP2R5E." (PMID 38184584, 2024). "In this study, we evaluated the correlation between ATF6 and CIP2A in patients with colon cancer." (PMID 30063110, 2018). "The clinicopathological characteristics in multivariate analysis by Cox regression, ATF6, were not a prognostic factor for survival, while CIP2A was independently associated with survival in patients with colon cancer and CRC." (PMID 30063110, 2018). "In addition, we also found that knockdown of CIP2A enhanced the tunicamycin‐induced cytotoxicity in colon cancer cells." (PMID 30063110, 2018). "Collectively, these results indicated that CIP2A may be a prognosis marker in the clinical prognosis of patients with colon cancer." (PMID 30063110, 2018). "In addition, the expression of CIP2A was crucial to sustain colon cancer cell survival under ER stress." (PMID 30063110, 2018). "Further investigation is warranted to determine whether knockdown of CIP2A could sensitize colon cancer cells to chemotherapy." (PMID 30063110, 2018). "Targeting CIP2A may disrupt ER stress‐mediated colon cancer cell survival and thus improve the prognosis of patients with colon cancer." (PMID 30063110, 2018). "Taken together, CIP2A is a promising biomarker for the prognosis of patients with colon cancer, and targeting ATF6‐CIP2A signaling might be a strategy for colon cancer therapy." (PMID 30063110, 2018). "Second, we showed that CIP2A is downregulated after inhibiting the MAPK pathway in three colon carcinoma cell lines; downregulation in cell lines harbouring a KRAS mutation (HCT116, SW620) is more pronounced than in Caco2 not harbouring a MAPK-pathway mutation." (PMID 24098375, 2013). "In the present study, we demonstrated that CIP2A expression is elevated in colon carcinoma samples, compared to its expression in normal, large intestine tissue, and that CIP2A expression is negatively correlated to both OS and clinical pathological parameters." (PMID 24098375, 2013). "CIP2A is overexpressed in head and neck squamous cell carcinomas and in colon carcinomas." (PMID 24098375, 2013). "To determine whether CIP2A expression is elevated in colon cancer and whether it might serve as a prognostic marker for survival, we analysed CIP2A mRNA expression by real-time PCR in 104 colon cancer samples." (PMID 24098375, 2013).
colon carcinoma (continued). "In addition, a multivariate analysis indicated that an advanced UICC-stage and high CIP2A expression (CIP2A above median and CIP2A expression used as a continuous marker) were independent prognostic factors for poor outcome in patients with colon cancer." (PMID 24098375, 2013). "Two findings support the hypothesis that CIP2A expression in colon cancer is downstream of the MAPK pathway." (PMID 24098375, 2013). "It is currently unclear what contributes to CIP2A overexpression in colon cancer." (PMID 24098375, 2013). "The aim of the present study was to address the relevance of CIP2A expression in colon cancer." (PMID 24098375, 2013). "In addition, CIP2A protein has been reported as an independent predictor of poor prognosis in colon cancer." (PMID 23342256, 2012). "Moreover, CIP2A protein expression determined the OS rates in patients with colon cancer." (PMID 30063110, 2018). "In human colon cancers (based on The Cancer Genome Atlas (TCGA) data), the expression of endogenous PP2A inhibitors, CIP2A and SET, correlated positively with the infiltration of CD8+ T cells and CD20+ B cells and negatively with FOXP3+ Treg cells." (PMID 34911954, 2021). "In connection with this, studies have shown that the expression of colon cancer oncogene CIP2A is positively correlated with the expression of ATF6, and ATF6, as a transcription factor, directly bind to the CIP2A promoter in turn." (PMID 34659567, 2021). "In the present study, we found that in patients with colon cancer, either ATF6 or CIP2A protein overexpression were negatively correlated to the OS rates." (PMID 30063110, 2018). "Expression of CIP2A was found to be dependent on MAPK activity, linking elevated c-Myc expression to deregulated signal transduction in colon cancer." (PMID 24098375, 2013). "For instance, CIP2A could inhibit PP2A activity by directly binding to c-myc with ser-62 site in human malignancies (head and neck squamous cell carcinoma or colon cancer)." (PMID 34984583, 2022). "Still, these effects are clearly cell type dependent as CIP2A depletion did not affect AKT phosphorylation in various colon cancer cell lines whereas it potently inhibited c-MYC expression 12,34." (PMID 25663244, 2015). "ATF6 was shown to sustain the expression of oncogenes such as BRCA1 or CIP2A (in vitro data in human colon cancer cell lines CaCO2, and SW480), as well as prevent DNA damage and to improve cancer cell viability, as observed in RKO and HCT116 colon cancer cell lines." (PMID 36902344, 2023).
triple-negative breast carcinoma (20 papers, 2012 to 2025). An invasive breast carcinoma which is negative for expression of estrogen receptor (ER), progesterone receptor (PR), and human epidermal growth factor receptor 2 (HER2). "Notably, LINC00665 also encodes a micro-peptide CIP2A-BP that promotes triple-negative breast cancer progression." (PMID 35563845, 2022). "The micro-peptide CIP2A-BP, encoded by LINC00665, can play an important inhibitory role in the progression of triple-negative breast cancer." (PMID 35563845, 2022). "As a tumor suppressor, the micro-peptide CIP2A-BP, encoded by LINC00665, can inhibit PI3K/AKT/NFκB signal transduction, thereby limiting the migration and invasion of triple-negative breast cancer cells." (PMID 35563845, 2022). "Apart from this, CIP2A-BP, a micro peptide encoded by LINC00665, was found to inhibit triple-negative breast cancer progression elsewhere." (PMID 34277412, 2021). "It has been shown that, in triple negative breast cancer, CIP2A has a half-life of 60 hours or more; however, 55% of the newly synthesized CIP2A is degraded in a relatively short time (24 hours)." (PMID 29805747, 2018). "Our previous data showed that 50 (87.7%) of 57 tumor samples from triple-negative breast cancer patients demonstrated variable CIP2A expression levels." (PMID 25228280, 2014). "This study reveals a novel mechanism by which bortezomib induces apoptosis in triple negative breast cancer cells (that is, CIP2A-dependent p-Akt downregulation)." (PMID 22537901, 2012). "However, recent identification of CIP2A as a central DNA damage response (DDR) protein essential for BRCA-mutated triple-negative breast cancer (TNBC) cells, indicates that CIP2A has broader role in cancer beyond MYC regulation." (PMID 36854761, 2023). "In triple-negative breast cancer, activated TGF-β/Smad4 signaling significantly increases the mRNA level of 4E-BP1, which inhibits the translation of the micro-peptide CIP2A-BP by binding it to eIF4F." (PMID 35563845, 2022). "This is in agreement with the results of a previous report showing that targeting SET downregulates the CIP2A mRNA and increases PP2A activity in triple-negative breast cancer cells." (PMID 34244560, 2021). "Bortezomib, a potent inhibitor of the 26S proteasome with broad anti-tumor effects, reportedly decreases the expression of CIP2A, another PP2A inhibitory protein, to exert anti-tumor effects on human triple negative breast cancer cells." (PMID 28655918, 2017).